BAG2 (BAG cochaperone 2)
Diseases named in the same sentence as BAG2 in open-access papers (continued):
Sharing a sentence is not in itself a finding about the gene and the disease.
tumor (21 papers, 2015 to 2026). "Further studies are required to elucidate whether serum BAG2 level is associated with BAG2 expression in either tumor cells or CAFs." (PMID 34572878, 2021). "The pathways affected are: Ephrin Receptor Signaling, TGF-β Signaling, STAT3 Pathway, EGF Signaling, Tumor Microenvironment Pathway, BAG2 Signaling Pathway, H-17A Signaling Pathway, EIF2 Signaling." (PMID 41717271, 2026). "The experimental results showed that shSTING effectively reversed the subcutaneous tumor suppression induced by BAG2 overexpression." (PMID 40364789, 2025). "The TIMER2 database showed that BAG2 expression is down‐regulated in most tumor types, especially in genitourinary tumors (including BLCA, CESC, KICH, KIRC, PRAD and UCEC)." (PMID 40364789, 2025). "Recent research demonstrates that under sensing arginine deficiency, SAMD4B is released by Bcl2-associated athanogene 2 (BAG2) and promotes β-catenin degradation to stabilize ATF4, thereby promoting tumor cell survival." (PMID 41154652, 2025). "Subcutaneous tumor‐bearing experiments showed that the tumors in the BAG2 group grew slowly, whereas the tumor growth rate was significantly enhanced in the shSTING group." (PMID 40364789, 2025). "Magnetic resonance imaging (MRI) and anatomical tissue results revealed that BAG2 overexpression significantly reduced subcutaneous tumor weight and volume compared to controls." (PMID 40364789, 2025). "The results demonstrated that BAG2 KO significantly augmented the protein expression of caspase-3 and caspase-9 in tumor tissues compared with controls." (PMID 40755756, 2025). "IHC staining of tumor tissues revealed reduced Ki67 protein levels in the BAG2 overexpression group." (PMID 40364789, 2025). "H&E staining provided additional evidence that the BAG2 group had fewer tumor lesions than the Vector group." (PMID 40364789, 2025). "Consistent with the results of the in vitro experiments, BAG2 KO significantly reduced tumor volume and slowed down tumor growth." (PMID 40755756, 2025). "The depletion of BAG2 facilitated the efficacy of paclitaxel (PTX) in suppressing SK-BR-3 tumor growth." (PMID 36593950, 2023). "Scramble or BAG2-silencing SK-BR-3 cells were orthotopically injected into the fat pads of mice, and tumor burden was measured regularly." (PMID 36593950, 2023). "The group with either positive BAG2 in CAF- or tumor-cytoplasm was related only with a higher rate of receipt of chemotherapy and radiotherapy." (PMID 34572878, 2021). "The results confirmed that the expression of BAG2 was significantly elevated in tumor tissues when compared with normal tissues (p < 0.05)." (PMID 34257542, 2021). "By analyzing the data from the TCGA_LIHC data set, we found that the transcriptional level of BAG2 was considerably increased in tumor tissues when compared with tumor-adjacent normal tissues (p < 0.001)." (PMID 34257542, 2021). "Bioinformatics analysis of the data from TCGA and GEO data sets, and IHC staining of BAG2 on collected tumor tissues and tumor-adjacent normal tissues all showed that BAG2 was significantly up-regulated in HCC when compared with normal liver samples." (PMID 34257542, 2021). "In this context, the prognostic impact of BAG2 cytoplasmic expression by tumor cells on DMFS, which was underscored in our previous study, was not statistically significant in this study." (PMID 34572878, 2021).
tumor (continued). "Correlation analysis was conducted independently between the expression of BAG2 and that of other genes in tumor samples of the TCGA_LIHC and GSE64041 data sets." (PMID 34257542, 2021). "Meanwhile, we analyzed BAG2 in immortal cell lines, tissues, and tumor pathology in Human Protein Atlas database." (PMID 32082999, 2020). "Considering that less than 10% of tumors had the amplification of BAG2 in majority of tumor types, it is possible that additional mechanisms contribute to BAG2 overexpression in tumors, which needs further investigation in future studies." (PMID 26271008, 2015). "Furthermore, tissue-level protein blotting experiments verified that downregulation of BAG2 resulted in increased expression levels of cleaved caspase-3 and cleaved caspase-9 in tumor tissues." (PMID 40755756, 2025). "Furthermore, a nude mouse transplantation tumor model with MKN-45 cells was established to further explore the effect of BAG2 on tumor growth in vivo." (PMID 40755756, 2025). "Importantly, patients with high BAG2 protein level had better overall survival outcomes and significantly lower tumor recurrence rates." (PMID 40364789, 2025). "In addition, IHC analysis of paired tumor tissues from the HUteS168Su01 cohort (paracancerous: n = 39, tumor: n = 39) showed that the protein level of BAG2 was significantly down‐regulated in tumor tissues." (PMID 40364789, 2025). "Notably, PET/CT scans demonstrated significantly less tumor activity and malignancy in mice in the BAG2 overexpression group compared to the control group." (PMID 40364789, 2025). "BAG2 expression was associated with tumor relapse status, but not correlated with HER2 status or lymph node metastasis." (PMID 36593950, 2023). "Since chemoresistance is associated with rapid recurrence, we first examined BAG2 expression in 26 primary tumor tissues, including 12 non-relapse tissues and 14 relapse tissues." (PMID 36593950, 2023). "BAG2 expression was evaluated by immunohistochemistry in CAFs or the tumor cells." (PMID 34572878, 2021). "This inconsistency indicates that BAG2 might function as an oncogene or a tumor-suppressor in tumors in a context-dependent way." (PMID 34257542, 2021). "Furthermore, we stratified the metastasis-free survival in these patients based on BAG2 expression in both CAFs and tumor cells." (PMID 34572878, 2021). "First, we evaluated the prognostic influence of cytoplasmic BAG2 expression in tumor cells." (PMID 34572878, 2021). "BAG2 might favor cell proliferation, repress apoptosis and facilitate tumor invasion in HCC, probably through regulation on ribosome biogenesis via genes like WDR12, BYSL, and DCAF13." (PMID 34257542, 2021). "Our results showed that enforced expression of miR-128 inhibited the HNSCC cell proliferation and tumor xenograft growth by mediating the expression of BMI-1, BAG-2, BAX, H3f3b, and Paip2 mRNAs, suggesting that miR-128 might act as a tumor suppressor." (PMID 25764126, 2015). "Furthermore, we constructed a popliteal lymph node metastasis model using U14 cells and showed that BAG2 overexpression greatly inhibited tumor migration in vivo, and that this effect could be reversed by depletion of STING." (PMID 40364789, 2025). "LOXL1 stabilizes BAG family molecular chaperone regulator 2 (BAG2) by preventing K186 ubiquitination, thereby inhibiting tumor apoptosis." (PMID 40786111, 2025). "Considering biopsies and resections together, there was a statistically significant difference of BAG2 and MAD2L1 expression levels in tumor tissues as compared to RMP." (PMID 39300217, 2024). "LOXL1 can stabilize BAG family molecular chaperone regulator 2(BAG2) by blocking K186 ubiquitination and inhibit tumor apoptosis." (PMID 36293126, 2022).
tumor (continued). "Significant factors in univariate analysis for DMFS were as follows: age less than 40 years old at the time of surgery, tumor size larger than 2 cm, nodal metastasis, LVI, and positive BAG2 expression in CAF." (PMID 34572878, 2021). "The observations from this study, that up-regulation of miR-128 inhibited HNSCC growth through directly mediating its targets Paip2, BAG-2, H3F3B, BMI-1, and BAX in proliferation and apoptotic pathways, support that miR-128 functions as a tumor suppressor." (PMID 25764126, 2015). "Indeed, in our subcutaneous tumor model, a significant increase in CD8+ T cell infiltration was observed in the BAG2 overexpression group." (PMID 40364789, 2025). "Consistent with this, cellular experiments showed that STING effectively reversed the changes in tumor activity induced by BAG2 knockdown or overexpression and was independent of HPV infection status." (PMID 40364789, 2025). "BAG2 expression in the CAFs and cytoplasm of tumor cells was classified as positive and negative, and low and high, respectively." (PMID 34572878, 2021). "With these pro-tumor effects in HCC, BAG2 at higher levels was found to be related to shorter survival of HCC patients and could serve as an independent prognostic marker." (PMID 34257542, 2021). "In vitro experiments showed that BAG2 might play a role in many biological behaviors of HCC, like favoring cell proliferation, repressing apoptosis and favoring tumor invasion." (PMID 34257542, 2021). "In addition, we conducted IHC staining of BAG2 on 10 HCC tissues and 10 tumor-adjacent normal tissues and scored the staining based on the intensity and extent." (PMID 34257542, 2021). "Importantly, the tumor recurrence group's BAG2 protein levels were lower than those of the no recurrence group." (PMID 40364789, 2025). "However, BAG2 positivity of CAFs was not related to larger tumor size, lymph node involvement, hormonal receptor status, or histological grade." (PMID 34572878, 2021).
neurodegenerative disease (6 papers, 2016 to 2025). A disorder of the central nervous system characterized by gradual and progressive loss of neural tissue and neurologic function. "The regulatory function of BAG2 via inhibition of CHIP activity has been reported to be involved in neurodegenerative diseases such as Parkinson disease and Alzheimer’s disease." (PMID 34572878, 2021). "RIC may act on the BAG2 Signaling pathway and is a potential mechanistic pathway for TBI-induced neurodegenerative disease processes." (PMID 32737368, 2020).
myopathies (2 papers, 2020 to 2022). "For example, mutations in DNAJB6 (homolog of dnj-24) lead to Limb-girdle muscular dystrophy 1E, and mutations in HSPB8 (homolog of hsp-12.2) or BAG2 (homolog of unc-23) were associated with myopathies." (PMID 35733850, 2022). "However, Bag2 knockdown in bag3+/+ or bag3+/- embryos did not result in (cardio-)myopathy." (PMID 33137814, 2020).
neurological diseases (2 papers, 2015 to 2023). "For the neurological disorder-associated proteins SPG20 and NEK9 as well as the co-chaperone BAG2, these alterations were confirmed by immunoblotting for biotinylated proximity partners of APEX2-SEC13 and -SEC16A in TECPR2 WT and MUT cells." (PMID 36797266, 2023).
BAG2 also shares sentences with these, for which no sentence is quoted: hepatocellular carcinoma (5 papers); fibrosarcoma (2); infection (2); oral cancer (2); sarcoma (2); colon cancer (1); colorectal tumors (1); glioblastoma (1); hereditary spastic paraplegia (1); lung squamous cell carcinoma (1); malignant pleural mesothelioma (1); multiple myeloma (1); muscular dystrophy (1); papillary thyroid carcinoma (1).